TYR (tyrosinase)
Diseases named in the same sentence as TYR in open-access papers (continued):
Sharing a sentence is not in itself a finding about the gene and the disease.
vitiligo (continued). "Possibly, the consequent accumulation of ROS might secondarily trigger autoimmunity and precipitate the depigmenting process of vitiligo, since ROS might alter the structure of protein involved in melanogenesis, such as tyrosinase, making them more antigenic." (PMID 25838868, 2015). "Interestingly, the use of imatinib can lead to vitiligo-like lesions, possibly due to inhibition of tyrosinase activity through the c-kit pathway blockade." (PMID 24385829, 2013). "It has been reported that tyrosinase may be an antigen for autoantibodies detected in vitiligo." (PMID 40837363, 2025). "In addition, although the oxidative stress theory has been mentioned in studies on the pathogenesis of vitiligo, it is worth noting that vitamin C, as an antioxidant, may exert inhibitory effects on tyrosinase activity by inducing cytoplasmic acidification." (PMID 39624091, 2024). "Furthermore, they detected significantly higher expression of miR-21-5p in exosomes from vitiligo patients and confirmed that miR-21-5p inhibits melanogenesis, as evidenced by changes in the levels of tyrosinase and tyrosinase-related protein 1 (TYP1) and tyrosinase-related protein 2 (TYP2)." (PMID 38106405, 2023). "An exception is represented by the TYR gene, which encodes for tyrosinase, a key enzyme in melanin biosynthesis that has been found in a GWAS performed on European White people with nonsegmental vitiligo." (PMID 36902341, 2023). "Additionally, an increased level of homocysteine, which is a tyrosinase inhibitor, may also be a contributing factor to the development of MetS in vitiligo patients." (PMID 34839983, 2022). "Therefore, tyrosinase is an important index for the treatment and diagnosis of vitiligo." (PMID 30174712, 2018). "This process might modify tyrosinase into a neoantigen possibly recognized by the immune system, thus triggering the autoimmune reaction at the basis of the depigmentation process observed in vitiligo." (PMID 25838868, 2015). "As expected, the expression of MC1R, TYR, TYRP1, and DCT was significantly downregulated during vitiligo pathogenesis." (PMID 38159176, 2024). "Cytokines (e.g., TNF-α and IL-6) -mediated inflammation is important in the development of vitiligo, and CHE and TYR are molecules related to melanin synthesis." (PMID 37575231, 2023). "Different antioxidants improve both vitiligo and melasma, with an increased minimal erythema dose (MED) following UV exposure being significant for vitiligo and tyrosinase inhibition being crucial for melasma." (PMID 38136202, 2023). "The antigens gp100 and tyrosinase are also expressed by melanocytes and can lead to cutaneous adverse events as one could see in the IMCgp100 trial with the occurrence of 83% rash, 69% pruritus, 25% erythema, 21% skin exfoliation, 20% hair color changes, and 16% vitiligo." (PMID 35185883, 2022). "Relative expression of melanogenesis-related genes MC1R, MITF, tyrosinase, TRP1, and TRP2 varied with age group, line of chicken, visual acuity, and vitiligo status." (PMID 35547230, 2022). "Flavonoid compounds such as chalcones extracted from Kaliziri can activate PI3K/Akt and GSK3β signaling pathways, increase tyrosinase (TYR) activity, promote the formation of epidermal melanin, and induce the recoloration of vitiligo." (PMID 35320978, 2022). "Expression of CSNK1G3, a gene related to human vitiligo, is significantly reduced in C57BL/6 black mice with tyrosinase-induced depigmented skin." (PMID 34220935, 2021). "Herein, TYR, TYRP1, DCT, and LARP7 were chosen as biomarkers to identify vitiligo by combining machine learning algorithm and WGCNA." (PMID 34107850, 2021). "TYR, TYRP1, TYRP2, and DCT mRNA levels in vitiligo patients are significantly downregulated and can lead to decreased melanin synthesis." (PMID 34107850, 2021). "Another study on melanocyte autophagy found that the expression of MITF, TYR, TYRP1, and TYRP2 proteins decreased in vitiligo patients." (PMID 34107850, 2021).
vitiligo (continued). "A critical role of Tregs in vitiligo has been demonstrated by histological studies in humans and in h3TA2 (human TIL derived Tyrosinase TCR transgenic on HLA-A2) vitiligo mouse models." (PMID 29371688, 2018). "In this study, tyrosinase expression is dramatically decreased in the mice treated with H2O2, which is similar to that in vitiligo patients' lesional skins." (PMID 29456788, 2017). "Consistent with the results of bioinformatics analysis, the expression levels of PPAR-γ, EDNRB, and TYR were significantly reduced in human non-segmental vitiligo skin along with the reduction of MITF, a key gene for epidermal melanogenesis." (PMID 38159176, 2024). "They found specific T cells against MART-1, gp100 and tyrosinase in the blood of both patients with MAL and vitiligo, although low levels were detected in MAL and stable vitiligo, while more melanocyte specific T cells were found in active vitiligo." (PMID 39421737, 2024). "By direct immunofluorescence, we examined the expression of PPAR-γ and melanogenesis-related genes EDNRB, MITF, and TYR in the skin tissues of non-segmental vitiligo patients (n = 5) and healthy people (n = 5)." (PMID 38159176, 2024). "The results showed that the expression of MITF and TYR was almost absent in non-segmental vitiligo lesions compared to healthy skin." (PMID 38159176, 2024). "The vitiligo inducer HQ used in our study can inhibit the expression of TYR proteins and increase the activity of CHE in serum, thus preventing the catalytic conversion of TYR to melanin." (PMID 37575231, 2023). "Similarly, in vitiligo, CD8+ T cells target antigens from melanosomal proteins such as PMEL, MLANA/MART1, TYR, TYRP1, and DCT." (PMID 37339630, 2023). "In this study, TYR expression also was elevated in SL eyes at 12 weeks (juveniles), independent of vitiligo status." (PMID 35547230, 2022). "In our study, we observed that 5D3PC derivatives could significantly increase tyrosinase activity and melanin content at concentrations of 10 μM and 50 μM in B16 cell, human melanocyte cell line (PIG1), and vitiligo melanocyte cell line (PIG3V)." (PMID 36430668, 2022). "TYR, TYRP1, DCT and LARP7 were identified as vitiligo-related biomarkers." (PMID 34107850, 2021). "TYR, TYRP1, DCT, and LARP7 were involved in the pathogenesis of vitiligo." (PMID 34107850, 2021). "Furthermore, the presence of autoantibodies against melanocyte antigens, including tyrosinase and tyrosinase-related protein (TYRP) 1 and 2, in the sera of vitiligo patients suggests an important role of humoral immunity in vitiligo pathophysiology." (PMID 33968147, 2021). "This may suggest a difference in pathogenesis between vitiligo and VKH involving tyrosinase as an autoantigen." (PMID 33384688, 2020). "Moreover, DCT, TYR, EDNRB and TYRP1 have also been reported previously playing a vital role in vitiligo." (PMID 32509450, 2020). "Tyrosinase (TYR) is a rate-limiting enzyme that is involved in the biosynthesis of melanocytes and thus, activation of TYR can increase the production of melanin and can be applied for treatment of vitiligo." (PMID 30400170, 2018). "Tyrosinase activity in vitiligo patients' lesional skins was lower than that in vitiligo patients' nonlesional skins." (PMID 29456788, 2017). "We assayed tyrosinase activity in ten lesional and nonlesional skins of vitiligo patients and observed that tyrosinase activity in lesional skins of patients was lower than nonlesional skins." (PMID 20418970, 2010). "Assay of specific diphenoloxidase activity of cell extract showed that the basal activity of tyrosinase in lesional skins of nonsegmental vitiligo patients were lower than nonlesional skins." (PMID 20418970, 2010). "93.75% of the vitiligo areas were negative for tyrosinase mRNA, including those that had positive Fontana-Masson staining for melanin." (PMID 16389417, 2005).
vitiligo (continued). "The activity of tyrosinase topromote melanogenesis (which is the process of producing melanin pigment in melanocytes) is known.Therefore, it is of interest to report the molecular docking analysis of tyrosinase (PDB: 1WX3) with compounds from poly-herbalformulation for vitiligo treatment." (PMID 40599915, 2025). "GA increases melanin production and distribution, improves tyrosinase activity, upregulates the expression of related genes and proteins through activation of MAPK and tyrosine metabolic pathways, downregulates oxidative stress, and then regulates changes in melanin synthesis to improve vitiligo." (PMID 40129935, 2025). "Overall, it seems that the inhibition of tyrosinase is crucial for melasma, whereas the reduction of inflammation, the decreased chemokine production, and lower inflammation following UV exposure (MED) are more characteristic of an effective antioxidant against vitiligo." (PMID 38136202, 2023). "When PMPP, together with Akt inhibitor IV, was introduced to cells in vitro, tyrosinase activity was inhibited, resulting in a severe decrease in melanin content, suggesting that MITF needs the PI3K pathway and that PMPP is a promising agent for the treatment of vitiligo." (PMID 37371141, 2023). "However, although antibodies reactive against melanocytes (e.g., anti-MelanA, anti-MCHR1, anti-tyrosinase, anti-gp100, and anti-tyrosine hydroxylase) have elevated serum titers in patients with vitiligo, they do not correlate with disease activity." (PMID 35643735, 2022). "Therefore, other differential genes which were enriched along with WNT6, DCT, TYR, EDNRB and TYRP1 by GO could provide more insights on vitiligo prognosis." (PMID 32509450, 2020). "Also, this study showed that tyrosinase activity in lesional skins of vitiligo patients was lower than their nonlesional skins and a meaningful correlation can be exist between increased of oxidative stress and decreased tyrosinase activity." (PMID 20418970, 2010). "Tyrosinase mRNA was negative in 93.75% of non-treated vitiligo areas." (PMID 16389417, 2005). "The mechanism by which PPIs induce vitiligo is not yet clear, but PPIs may impair melanogenesis by inhibiting the H + /K ± ATPase on melanosomal membranes, disrupting the pH gradient crucial for tyrosinase activation." (PMID 40920788, 2025). "Subsequently, the results of immunofluorescence staining showed that the expression levels of PPAR-γ, TYR, and EDNRB were significantly reduced in non-segmental vitiligo patients’ lesions skin along with the number of MITF-labeled melanocytes." (PMID 38159176, 2024).
melasma (77 papers, 2012 to 2026). "We also report a significant association in the codominant allele models for rs1042602 of the TYR gene, particularly in the CC genotype, between the melasma vs. control groups." (PMID 39940926, 2025). "Oral retinoids such as isotretinoin or alitretinoin also aggravate melasma, with the underlying mechanisms of hormonal imbalances or directly enhancing TYR expression, respectively." (PMID 41154805, 2025). "A pilot study in African women with melasma indicated that the rs1042602 single-nucleotide polymorphisms (SNP) in the TYR gene showed a strong association with melasma, with the AA genotype conferring a markedly increased risk." (PMID 41154805, 2025). "The rs1042602 polymorphism of the TYR gene was strongly associated with melasma development, particularly the CC genotype, indicating its potential role in developing hyperpigmentation disorders." (PMID 39940926, 2025). "For example, the rs1042602 Single Nucleotide Polymorphisms (SNP) in the TYR gene showed a strong association with melasma, with the AA genotype conferring a markedly increased risk." (PMID 39940926, 2025). "We also report a significant association between the melasma vs. control groups in the codominant allele models for rs1042602 of the TYR gene, particularly in the CC genotype." (PMID 39940926, 2025). "Overproduction of melanin driven by tyrosinase hyperactivity is directly linked to hyperpigmentation disorders such as solar lentigo, chloasma, and freckles, which can markedly alter phenotypic appearance." (PMID 40939092, 2025). "Melasma treatment primarily eliminates melanosomes by facilitating their excretion via the inhibition of tyrosinase and associated proteins." (PMID 39731267, 2025). "Pigmentary disorders due to unusual tyrosinase activity causes hyperpigmentation and in turn dermatological disorders including melasma, melanoderma, freckles, and ephelides." (PMID 39209920, 2024). "Tyrosinase has been implicated in skin diseases and esthetic characteristics such as freckles, melasma, age spots, and in Parkinson’s and Huntington’s diseases." (PMID 38137266, 2023). "Increased melanin synthesis due to tyrosinase hyperactivity can cause hyperpigmentation disorders, which in consequence causes freckles, age spots, melasma, or postinflammatory hyperpigmentation." (PMID 36615251, 2022). "In the presence of low levels of testosterone, the activity of adenosine monophosphate and tyrosinase increases, causing melasma." (PMID 36942149, 2022). "Tyrosinase is the main factor causing some dermatological diseases including freckles, age spots, and melasma." (PMID 33488760, 2021). "Overexpression of the tyrosinase gene severely caused hyperpigmentation disease, such as freckle, chloasma, and senile plaque." (PMID 25045392, 2014). "Overexpression of tyrosinase can cause excessive production of melanin and lead to hyperpigmentation disorders, including melasma and freckles." (PMID 23304221, 2012). "A recent study looked at how melon seed affects melasma and discovered that the anti‐tyrosinase properties of the seeds, when mixed with chickpeas (10%), may effectively improve spots caused by melasma." (PMID 39710951, 2025). "Overactivity of tyrosinase has been linked to excessive production of melanin pigments, which results in the development of different dermatological disorders such as wrinkles, lentigo, skin aging spots, melasma, nevus, freckles, and melanoma." (PMID 38247479, 2023). "However, excessive tyrosinase can cause uneven pigment distribution and localized pigmentation, which can lead to freckles, chloasma and even malignant melanoma." (PMID 36557801, 2022). "Excessive tyrosinase can cause freckles, melasma, skin cancer, and age spots." (PMID 34811448, 2021). "Tyrosinase accumulation may cause dermatological disorders such as melasma and age spots; therefore, inhibition of tyrosinase may contribute to depigmentation." (PMID 31284438, 2019).
melasma (continued). "In the body, it also suppresses TYR activity, disrupting melanin and keratinocyte formation and helping alleviate symptoms in melasma patients." (PMID 40640993, 2026). "In this study, Sanger sequencing of pharyngeal swabs from melasma populations and genomic association analysis revealed that TYR and DCT were the relevant genetic loci for melasma." (PMID 40369904, 2025). "Significant associations were observed for the TYR gene (rs1042602), HERC2 gene (rs1129038), and SLC24A5 gene (rs1426654) polymorphisms, highlighting their potential roles in melasma susceptibility." (PMID 39940926, 2025). "Tyrosinase is a widely recognized strategy for managing hyperpigmentation conditions like melasma, freckles, and age spots." (PMID 40807342, 2025). "This study investigates the association between genetic variants in SLC45A2, TYR, HERC2, and SLC24A5 genes and the severity of melasma in women of reproductive age." (PMID 39940926, 2025). "Sanger sequencing of pharyngeal swabs from 80 patients with melasma combined with genomic association analysis showed that TYR and DCT were the relevant genetic loci for melasma." (PMID 40369904, 2025). "The potential mechanism of PE extract against melasma was predicted to target the CREB1/MITF/TYR/DCT axis." (PMID 40369904, 2025). "Overactivity of tyrosinase can lead to hyperpigmentation disorders, including melasma, freckles, and age spots." (PMID 41301228, 2025). "Pearl can alleviate melasma by targeting the CREB1/MITF axis and then the melasma‐related gene loci TYR and DCT." (PMID 40369904, 2025). "Kojic acid, a fungal product that is hydrophilic in nature, is useful in hyperpigmentation disorders like melasma, due to its inhibitory action on tyrosinase production and also serves as a potent antioxidant." (PMID 40296942, 2025). "The sorrel plant reduces melanin production with a tyrosinase inhibition mechanism and thus effectively improves hyperpigmentation disorders such as melasma." (PMID 39710951, 2025). "With reference to some previous clinical studies, some medicinal plants with tyrosinase inhibitory activity like licorice, mulberry and ginseng showed promising efficacy in treating melasma." (PMID 40255950, 2024). "Due to these properties, phenolic compounds can be used in the cosmetic industry, inhibiting the enzyme tyrosinase, which is over expressed in skin features such as melasma, freckles, and senile lentigines." (PMID 38928737, 2024). "Kojic acid can be effective in melasma management through the inhibition of free tyrosinase synthesis." (PMID 38628650, 2024). "T. chebula antioxidant, anti-inflammatory and tyrosinase enzyme inhibitory activities make it a good choice for treating melasma." (PMID 40255950, 2024). "Tyrosinase (TYR) is related to pigmented skin diseases such as chloasma and senile plaques, and acetylcholinesterase (ACHE) is related to Alzheimer’s disease." (PMID 37241909, 2023). "Hyperpigmentation is a medical and cosmetic problem caused by an excess accumulation of melanin or the overexpression of the enzyme tyrosinase, leading to several skin disorders, i.e., freckles, melasma, and skin cancer." (PMID 36834568, 2023). "Azelaic acid has been proven to suppress tyrosinase activity, diminish the formation of aberrant melanocytes, and have anti-inflammatory characteristics, making it an appealing alternative to melasma therapy." (PMID 37457606, 2023). "The findings of this study inform the possible commercialisation of C. flanaganii as a tyrosinase inhibitor derived from a medicinal plant, in support of melasma treatment." (PMID 37375906, 2023). "Inhibition of tyrosinase has major roles and applications, e.g., in biomedicine, to contrast skin pigmentation disorders like melasma and in food safety, to prevent enzymatic food oxidative spoilage on storage." (PMID 37760066, 2023).